IL1B (interleukin 1 beta)
Diseases named in the same sentence as IL1B in open-access papers (continued):
Sharing a sentence is not in itself a finding about the gene and the disease.
asthma (continued). "In addition, the protein expression levels of NLRP3, caspase-1, cleaved caspase-1, GSDMD, GSDMD-N, IL-18, and IL-1β were increased, indicating that MUC1, TLR4/MyD88/NF-κB pathway, and NLRP3-induced pyroptosis are involved in the pathogenesis of asthma." (PMID 37880668, 2023). "PBMCs from patients with severe asthma released more IL-1β in response to LPS + nigericin than those from non-severe asthma." (PMID 38044426, 2023). "PBMCs from patients with non-severe or severe asthma produced more IL-1β in response to nigericin than those from healthy subjects." (PMID 38044426, 2023). "Cytokines, e.g. TNF, IL1β, IL5, IL6, IL12 and IL23, represent important therapeutic targets in immune-mediated inflammatory diseases (IMIDs), such as inflammatory bowel disease (IBD), psoriasis, asthma, rheumatoid and juvenile arthritis." (PMID 35731827, 2022). "However, the IL-1β level in lung tissue homogenates and the TNF-α level in BALF were significantly higher in the asthma and ACO-a models than in the control." (PMID 36474247, 2022). "On the other hand, both DTX and NOE were able to reduce IL-1B levels compared to the asthma group but were not statistically significant." (PMID 35774748, 2022). "IL-1β release mediates the release of other inflammatory cytokines, including TNF-α and IL-6, which play essential roles in the pathogenesis of pulmonary diseases such as asthma, pulmonary fibrosis, and COPD." (PMID 36432032, 2022). "In conclusion, our study shows that bergenin regulates the NF-κB pathway and blocks p65 translocation into the nucleus by activating SIRT1, thereby reducing the release of proinflammatory factors (such as IL-1β, IL-5, IL-6, and MMP-9 by macrophages) to play a role in asthma treatment." (PMID 36313381, 2022). "In a mouse obese asthma model, ILC3 stimulated by IL-1β, IL-6, or IL-23 produced IL-17A." (PMID 35626330, 2022). "Similarly, mice with OVA-induced asthma showed a significantly higher expression of NLRP3, Caspase-1, IL-1β in lung tissues, and QF can significantly downregulate the expression levels of these proteins." (PMID 36081945, 2022). "The obtained results showed that OVA-sensitive rats significantly increased the levels of pro-inflammatory cytokines IL-1B, TGF-β, and SMA-α compared to the control group (p < 0.05), while treatment with NOE remarkably reduced the SMA-α gene expression compared to the asthma group (p < 0.05)." (PMID 35774748, 2022). "Here we report an adjuvant function of IL-1β in promoting allergen-triggered skin sensitization and asthma, rather than an immune regulation function on its own." (PMID 36050303, 2022). "In addition, the concentrations of IL-4, IL-5, and IL-13, as well as IL-1β, IL-6, and TNF-α, were greatly elevated in BALF and lung tissues, especially in lung tissues, of asthma mice, which were suppressed after the treatment of Ferr-1 and/or 3-MA." (PMID 35154576, 2022). "In respiratory diseases and asthma, cytokines promote the survival of inflammatory cells, contributing to the maintenance of chronic inflammation and producing proinflammatory cytokines such as IL-1β, IL-6, and TNF-α, which are increased in the sputum and BALF of patients with asthma." (PMID 36555240, 2022). "In T2 asthma, the Th2 cytokines IL-4, IL-5, IL-9, IL-13, and IL-25, and the acute proinflammatory cytokines TNF-α, IL-1β, IL-6, and IL-8, subsequently lead to bronchial hyperresponsiveness (BHR), and plasma cells and antibody-producing cells secrete antibodies." (PMID 36430662, 2022). "Furthermore, it was found that the levels of TNF-α, IL-1β, IL-4, IL-5, and IL-13 in the BALF, and the levels of IL-17, IL-6, and OVA-specific IgE were observably increased in serum of RSV-infected asthma mice, while the level of IFN-γ was decreased." (PMID 36213326, 2022).
asthma (continued). "Moreover, Th1 cells, Th17 cells, ILC1s, ILC3s, and M1 macrophages are involved in this endotype, and their production IL‐1β, IL‐6, IL‐17, IFN‐γ, and TNF‐α are responsible for the recruitment and activation of inflammatory cells during asthma attacks." (PMID 36051916, 2022). "Expression of the cytokines TNF-α, IL-1β, IL-6, IL-5, and IL-8 were increased in placentae of female, but not male fetus, in pregnancies complicated by asthma." (PMID 36046194, 2022). "Finally, progesterone stimulates the production of proinflammatory cells and upregulates the expression of cytokines and proteins such as IL10, IL-1β, IL-5, IL-6, IL-22, IL-4, IL-17A, TNFα, and GATA 3 through the regulation of receptors in asthma." (PMID 35096261, 2021). "When ASM cells were treated with a variety of cytokines found in high levels in the airways of asthma such as TNFα, IL-1β, Th1 (IFN-γ), Th2 (IL-4, IL-9, and IL-13), and Th17 (IL-17) cytokines, only TNF and IL-1β were able to increase pentraxin-3 secretion significantly." (PMID 35387000, 2021). "UPM stimulation did not alter the IL-1β level in epithelial cultures compared to corresponding unstimulated control cells, asthma and COPD patients." (PMID 34168212, 2021). "Therefore, we measured IL-1β, IL-6, and TNF-α levels to indirectly verify the maturity of DCs in patients with asthma." (PMID 33503170, 2021). "Here, we show that asthma exacerbation is triggered by airway macrophages through a prion-like cell-to-cell transmission of extracellular particulates, including ASC protein, that assemble inflammasomes and mediate IL-1β production." (PMID 34423792, 2021). "In severe asthma, especially in patients resistant to glucocorticoid therapy, the M1 macrophage phenotype predominates, producing numerous pro-inflammatory mediators, such as TNF-α, IL-1β and NO, which aggravate lung injury and accelerate airway remodeling." (PMID 34281592, 2021). "In ACO mice, there was an overlap of asthma and COPD with marked increases of total leukocytes, neutrophils, and eosinophils counts and higher levels of inflammatory cytokines (IL-4, IL-6, TNF-α, IL-1β, IL-17A, and IFN-γ) in BALF." (PMID 33869177, 2021). "In the inflammatory response, proinflammatory cytokines, such as IL-1β, IL-6, and TNF-α, activate the body's immune system and promote the aggregation and activation of inflammatory cells, which plays a crucial role in the process of asthma." (PMID 34966437, 2021). "ACO patients were found to have significantly higher levels of IL-1β than controls; however, levels were not as high as observed in asthma or COPD." (PMID 32448302, 2020). "Here, we have analyzed the levels of cytokines such as IL-13, IFN-γ, TNF-α, IL-4, IL-5, and IL-1β and growth factors such as HGF, VEGF, and CSF2 or GM-CSF along with the estimation of serum S1P concentration in asthma patients compared with the healthy controls." (PMID 32637407, 2020). "On the other hand, NLRP3 activation and IL-1β release do not appear to be required for the activation of TH2 immunity by uric acid during asthma development, but this pathway is suggested to be important for skin TH2 responses." (PMID 33584721, 2020). "Cells of the immortalized murine macrophage cell line RAW264.7 were treated with cytokines that are known to act in the pathology of asthma (CytoMix), i.e. IFNγ, IL-1β, and TNFα in the presence or absence of recombinant Grx2 WT or Grx2 C40S." (PMID 33224135, 2020). "This flavonoid also inhibited the activation of NF-κB and STAT-1 in macrophages, and reduced inflammatory cytokines including; TNF-α, IL-6, IL-1β and PGE2 and also increased inflammatory cytokines in vitro, which it can useful for the treatment of allergic disorders such as asthma." (PMID 33295229, 2020).
asthma (continued). "The use of the NLRP3 inhibitor MCC950, the caspase-1 inhibitor Ac-YVAD-CHO and IL-1β neutralizing antibodies effectively reduce the asthma-induced inflammatory response, indicating that activation of the NLRP3 inflammasome and induction of IL-1β are important components in inflammation in the body." (PMID 32293543, 2020). "In fact, both cytokines, IL-1β and IL-1α, reduced in our study by brine solution, were displayed to play a significant role in AHR and inflammatory cells influx; their blockade reduced the phenotype of murine asthma." (PMID 32645931, 2020). "Higher levels of YKL-40 were associated with increased T1 inflammatory biomarkers such as IL-1β and IL-6, indicating that YKL-40 may be useful in predicting exacerbation rates and responses to asthma treatment regimens." (PMID 31113430, 2019). "IL-1β is capable of enhancing the production of immunomodulatory mediators, which are required for extracellular matrix (ECM) degradation and airway remodeling in asthma." (PMID 30373775, 2019). "The upregulated expression levels of IL-1β, IL-6, IL-12, IL-17A, KC, MCP-1 and TNF-α may contribute to airway neutrophilia and asthma exacerbation." (PMID 31889961, 2019). "The level of IL-1β (P < 0.05) and MDA in the serum and lung tissue (P < 0.01), (P < 0.05), and also the level of TNF-α (P < 0.05) in the lung tissue decreased in the Myrtenol group compared to the asthma group." (PMID 32641957, 2019). "Furthermore, the expression of serum IL-1β, IL-4 and IL-17F was higher in the asthmatic model compared to those being transplanted by mASCs, indicating that cell therapy might improve the degree of asthma airway inflammation and airway remodeling through regulating the Th1/Th2 ratio." (PMID 30089474, 2018). "This concerns unexpected observations of particular interest including potential roles of IL-1β, in Th2 aspects of viral induced exacerbations yet lack of a role in allergic mouse asthma." (PMID 29361942, 2018). "In addition to ILC2, a team conducting experiments in mouse models of HFD concluded that NLRP3, IL-1β, and ILC3 cells facilitated obesity-related asthma by mediating inflammation." (PMID 30050954, 2018). "The main limitation of our study is that the role of IL-1β in HFD-induced asthma is not confirmed in mechanistic experiments using IL-1β knock out mice or IL-1β receptor blockers." (PMID 29686414, 2018). "As an important driver of inflammation in the bronchial epithelium, we showed that PAF stimulation increased the expression of IL-6, IL-1β, and TNF-α in HSAECs, and this effect was reduced by HSYA, thus potentially attenuating the secretion of inflammatory cytokines in asthma patients." (PMID 30123133, 2018). "Based on the present data we suggest that IL-1β is a participating factor in viral induced asthma exacerbations but not in baseline allergic conditions." (PMID 29361942, 2018). "Moreover, serum vitamin D levels were inversely correlated with airway resistance, total inflammatory cells, and IL-1β and IL-17 concentrations in BALF, suggesting that vitamin D3 level is a potential predictor for obese asthma." (PMID 29160418, 2017). "Furthermore, obese asthma mice exhibited significantly lower vitamin D levels in serum and significantly higher NLRP3 and IL-1β mRNA expression levels in lung tissue." (PMID 29160418, 2017). "Comparatively similar levels were recorded for nine out of the 10 cytokines measured [e.g., – Interleukin (IL)-1β, IL-6, IL-10], regardless of study participant asthma status." (PMID 28424616, 2017). "The transient increase of lung IL-17A could be mediated through transient circulating levels of adipose-tissue-originated IL-1β and IL-23, suggesting a WAT-lung axis in “metabolic programming” of asthma in adulthood." (PMID 27087690, 2016).
asthma (continued). "Our findings with VVHE suggest that the V. vinifera fruits could act in asthma via its neutralizing effects on TH2 derived pro-inflammatory (TNF and IL-1β) and inflammatory (IL-4 and IL-5) cytokines, key elements in the pathophysiology of bronchial asthma." (PMID 27536321, 2016). "The serum samples of these mice also had lower IL-1β (all P < 0.05), TNF-α (all P < 0.05), IL-4 (all P < 0.05) and IL-5 (all P < 0.05) levels and higher levels of IFN-γ (P < 0.001) compared with the OVA-induced asthma mouse model." (PMID 27134644, 2016). "When macrophages are deficient in gal-3 there is increased responses to LPS, reduced bacterial replication and increased expression of IL-1β, TLR2 and IL-6, which are similar observations to those we have previously reported in patients with the neutrophilic subtype of asthma and COPD." (PMID 25616863, 2015). "Although the level of IL-1RA was not different between the asthma inflammatory subtypes, the ratio of IL-1RA to IL-1β was significantly lower in NA compared with EA and PGA." (PMID 25616863, 2015). "Consistent with this is a previous study in chronic persistent severe asthma (n = 9) which demonstrated increased mRNA expression of the innate immune receptors TLR2, TLR4 and CD14, as well as the cytokines IL-8 and IL-1β in induced sputum from patients with neutrophilic asthma." (PMID 24955983, 2014). "The regulatory effects of IL-1β and TNF-α on ASM cell proliferation could have important consequences for development of asthma therapeutics." (PMID 23388501, 2013). "The acute model of asthma had elevated levels of circulating serum IL-1β relative to controls, whose levels were not detectable (n = 8, p < 0.001)." (PMID 20974000, 2010). "None of the well-defined asthma/inflammatory genes (Il1b, Il4, Il10, Il13, Il6, Tnfa, Infg, Tgfb1) are differentially expressed, although they connect many of the genes that are." (PMID 18087596, 2007). "The massive IL-18 and IL-1β release from pyroptotic AECs and macrophages may influence the differentiation, proliferation and function of CD4+ T cells, and determine the course of asthma progression." (PMID 39611173, 2024). "Additional research has demonstrated that IL-1β, IL-6, anti-IFN-γ, and IL-21, which is a cytokine environment that stimulates T cells in asthma to differentiate into the same biphenotypic cells, promote dual-positive TH2/TH17 cell differentiation, worsening asthma." (PMID 39439788, 2024). "IL-1β produced after the activation of NLRP3 inflammasome positively regulates the differentiation of Th17 cells, which promotes the secretion of IL-6 and IL-8 and induces neutrophil recruitment, which may be an important factor in the acute attack of asthma." (PMID 38117410, 2024). "Although many investigations have found p38 MAPK activities in blood and in airway epithelial cells to be increased in severe asthma, in our data p38 did not respond in the early hours of IL-1β stimulation, suggesting that it is not a major pathway for cytokines stress." (PMID 39030600, 2024). "Finally, DEP stimulation alone increased pro-IL-1β priming in controls and in asthma, but it did not have any effect on RV-induced RIG-I inflammasome activation in the bronchial epithelium of any group." (PMID 37087523, 2023). "However, following treatment with LPS + nigericin, PBMCs from patients with severe asthma released increased IL-1β levels compared to PBMCs from patients with non-severe asthma and healthy subjects." (PMID 38044426, 2023). "However, following treatment with nigericin, PBMCs from patients with severe or non-severe asthma had increased IL-1β release compared to PBMCs from healthy subjects." (PMID 38044426, 2023). "Importantly, we highlight that NLRP3 inflammasome-mediated IL-1β responses can be therapeutically suppressed in systemic immune cells from patients across all subtypes of both severe and non-severe asthma." (PMID 38044426, 2023).
asthma (continued). "However, OS biomarkers NO2−, lipid peroxide, protein sulfhydrils, and inflammatory biomarkers TNFα, IL-4, IL-37, IL-1β, IL-1RL1, IL-1R1, NLRP3, and TGF-β1 showed positive association with asthma in nonsmokers, but not in smokers." (PMID 37367073, 2023). "Interestingly, nigericin-induced IL-1β release from PBMCs from asthma subjects positively correlated with neutrophil, but not eosinophil number or percentage in patient sputum, and negatively correlated with FEV1 and FVC, but not FEV1/FVC." (PMID 38044426, 2023). "Interestingly, however, in contrast to HDM extract, A. alternata alone was able to induce a potent release of mature IL-1β only in asthma, but not in healthy individuals." (PMID 37087523, 2023). "Additionally, CAD and CAD-contained serum attenuated the up-regulated expressions of Bax, Cleaved caspase-3, NLRP3, ASC, Cleaved caspase-1, GSDMD-N, IL-18, IL-1β, TLR3, p-P65, p-IκBα, and IRF3 but increased Bcl-1 and GSDMD levels in the asthma mice and LPS-induced 16HBE cells, respectively." (PMID 36213326, 2022). "Various cytokines, including TNF-α, transforming growth factor-β (TGF-β), IL-1β, and platelet-derived growth factor (PDGF-BB), have been found to be important mediators of airway remodeling and fibrotic responses, and they can also initiate and drive the inflammatory response in asthma." (PMID 35172671, 2022). "The animal experiments verified that Danlong Dingchuan Decoction could effectively reduce IL-4, IL-6, IL-8, and IL-1β expression in the lung tissue of asthmatic mice, decrease TLR4 mRNA expression, and inhibit Th2 cytokine-mediated inflammatory response to treat asthma." (PMID 35186104, 2022). "Moreover, the excessive synthesis by the adipose tissue of pro-inflammatory cytokines, such as IL-1β, IL-6, TNF-α, and TGF-β, may contribute to asthma pathogenesis." (PMID 35807067, 2022). "Similarly, compared to the control mice, mice with OVA-induced asthma showed a significantly higher expression of NLRP3, Caspase-1, IL-1β in the lung tissues, and the expression of these key proteins was significantly decreased in asthmatic mice treated with QF." (PMID 36081945, 2022). "Due to the small sample size of asthmatics with at least one exacerbation during six months of follow-up period (only three patients), we could not analyze the relationship between IL-1β mRNA expression and asthma exacerbation in our study." (PMID 34344357, 2021). "Subsequently, the OVA-induced asthma mice were treated with M2Φ-Exos, and we found a significant inhibition in fibrosis and cell apoptosis in mouse lung tissues, a reduction in the number of granulocytes, and a decline in the secretion of OVA-induced IL-1β, IL-6, TNF-α, and MCP-1." (PMID 33994863, 2021). "In the present study, we documented immunomodulatory mechanisms of GSYJ that relieve asthma symptoms, including AHR, lung inflammatory cell infiltration, and increased serum total IgE levels by regulating the expression of IL-5, IL-6, IFN-γ, IL-12, IL-1β, RANTES, and iNOS." (PMID 33708257, 2021). "Similarly, gemcitabine is another candidate drug in the asthma-COPD and its intranasal administration significantly reduces viruses and the inflammation of lungs and the anti-inflammatory cytokines including TNF-α and IL-1b." (PMID 31952466, 2020). "Both the six gene signature (6GS: CPA3, DNASE1L3, CLC, IL1B, ALPL, and CXCR2) and T‐helper 2 signature (TH2S: CLCA1, SERPINB2, and POSTN) are proposed as biomarkers in the identification of inflammatory phenotypes of asthma in induced sputum and epithelial brushings, respectively." (PMID 31903716, 2020). "Increased expression of NLRP3 and IL-1β was also detected in the sputum of patients with SA compared to MMA, and correlated with clinical parameters of disease, such as neutrophilic airway inflammation, Asthma Control Questionnaire (ACQ) score, and Forced Expiratory Volume in 1 second (FEV1)%." (PMID 31590215, 2019).